ARF6 (ARF GTPase 6)
Diseases named in the same sentence as ARF6 in open-access papers (continued):
Sharing a sentence is not in itself a finding about the gene and the disease.
tumor (continued). "Using a Drosophila tumour model, we show that Egfr cooperates with oncogenic Ras via Arf6, which functions as a novel regulator of Hh signalling." (PMID 28281543, 2017). "In this study, using a Drosophila tumour model the authors demonstrate that depletion of Arf6, a Ras-related GTP-binding protein activated by EGFR, supresses oncogenic Ras driven overgrowth via modulation of Hedgehog signalling." (PMID 28281543, 2017). "Taken together, these data indicate that Arf6 regulates Hh signalling in Ras tumours and during development." (PMID 28281543, 2017). "Removing Spi or Egfr function in RasV12 clones (RasV12, spi_ or RasV12, Egfr_ double mutant cells) showed similar effects, consistent with the notion that Egfr/Arf6 signalling stimulates Hh signalling in Ras tumours." (PMID 28281543, 2017). "Our results clearly show that LPA has another basic function in promoting tumour malignancy, via the activation of Arf6." (PMID 26854204, 2016). "We also demonstrate that ARF1 and ARF6 control major processes that increase tumor metastasis in vivo such as cell motility, migration, proliferation, and resistance to apoptosis." (PMID 26908458, 2016). "Although the numbers of tumours are relatively small in this study, we made a preliminary assessment of the patterns of Gleason scores (7, 8 and 9) relative to ARF6 intensity." (PMID 26185744, 2015). "Analysis of pancreatic xenograft tumors derived from control-RNAi S2-013 cells showed that cytoplasmic granular IGF2BP3 was mainly observed in the tumor penumbra, and ARF6 was strongly expressed near cell membranes in the penumbra." (PMID 25216519, 2014). "Our illustration of arf6 mediated increased budding and MPs excretion once again illustrate the complexity of the cross-talk between tumor and stroma." (PMID 24424657, 2014). "The Akt activation in ECs increased Arf6 expression and functionalized a MPs dependent vascular niche enhancing tumor cells pro-metastatic properties." (PMID 24424657, 2014). "She noted that ARF6 is known to play multiple roles at the cell periphery and in her work she has shown a direct correlation between ARF6 activation and tumour progression." (PMID 26082318, 2013). "She noted that ARF6 activation promotes the formation of invadopodia which enhance tumour invasiveness, and also stimulates the biogenesis of microvesicles that are enriched for the active form of ARF6." (PMID 26082318, 2013). "On the other hand, we have provided several lines of evidence that AMAP1 acts as an effector for Arf6 in tumor invasion, in addition to its function as a GAP for other Arf isoforms." (PMID 19416474, 2009). "Thus, inhibition of MAPK or ARF6 were equally cytostatic, but cell viability persisted above the baseline viability at time zero, indicating a low level of tumor cell survival." (PMID 40909781, 2025). "ARF6 plays a crucial role in regulating vesicle transport and membrane lipid remodeling, its overexpression in cancers like pancreatic and BC contributes to tumor invasion, metastasis, and immune evasion." (PMID 40141028, 2025). "Additionally, we found that patients with poor tumor differentiation, advanced TNM stage, tumor recurrence, and incomplete tumor encapsulation had higher ARF6 expression." (PMID 37716993, 2023). "In vivo nude mouse xenograft models showed that ARF6 enhanced tumor growth." (PMID 37716993, 2023). "Besides influencing tumor metastasis, ARF6 enhances tumor proliferation by activating phospholipase D." (PMID 37716993, 2023). "The ARF6-based pathway plays a significant role in vascular ECs, may affect the CNS as well as tumor malignancy, and targeting ARF6 or components of its downstream signaling pathways may have extensive therapeutic implications for many diseases." (PMID 37834383, 2023). "Furthermore, after intervening of STAT3, the effect of ARF6 on tumor-promoting was weakened, which demonstrated ARF6 functioned through STAT3 signaling in HCC." (PMID 37716993, 2023).
tumor (continued). "ARF6-PLD-mTORC1-S6K1/4E-BP1 axis enhanced tumor cell proliferation." (PMID 37716993, 2023). "Similarly, inhibition of STAT3 by Stattic evidently abrogated the tumor growth induced by active ARF6 overexpression in Huh7 cells." (PMID 37716993, 2023). "ADP-ribosylation factor 6 (ARF6) governs the trafficking of bioactive cargos to tumor-derived microvesicles (TMVs) which comprise a class of extracellular vesicles released from tumor cells that facilitate communication between the tumor and the surrounding microenvironment." (PMID 36775056, 2023). "Additionally, studies have shown that IPCEF1 induces tumor metastasis by activating the Arf6 pathway." (PMID 35634509, 2022). "Furthermore, recently an ARF6-exportin 5 dependent pathway was described for the packaging of miRNAs into tumor-derived MVs." (PMID 36045692, 2022). "Similarly, when the EAC cores were separated based on tumour grade, an increase in ARF6 expression was seen to correlate with tumour grade; reaching significant levels in grades II (although not statistically significant; p = 0.3415) and III (p = 0.0122)." (PMID 35143561, 2022). "Furthermore, we detected the expression of ARF6 and N-Cadherin, which are related to tumor cell proliferation, adhesion and migration ability." (PMID 34991661, 2022). "Taken together, DUSPs exert their tumor suppressor function through complex interaction networks and some of them may be correlated with ARF6 expression." (PMID 36017891, 2022). "Furthermore, our analysis of PDAC tumor specimens demonstrated that high ARF6 level is correlated with low DUSP6 level." (PMID 36017891, 2022). "Moreover, ARF6 is required for DDR1-mediated tumor cell migration and invasion, suggesting that ARF6 and DDR1 function together to regulate the development of HCC." (PMID 35140331, 2022). "EGFR also activates ARF6 to stimulate oncogenic Ras tumor overgrowth by regulating Hh signaling." (PMID 36224181, 2022). "ARF6 has many other roles in regulating multiple physiological and pathological processes, including cell membrane ruffle formation and adhesion, tumor formation, tumor cell proliferation, migration, invasion and metastasis." (PMID 34621682, 2021). "Then, glypicans and Arf6 may promote tumor cell migration and metastasis through affecting the degradation of β-catenin in the Wnt pathway." (PMID 33777320, 2021). "Strikingly, IQSEC1, ARF5 and ARF6 increase similarly stratified patient survival when all tumour types were considered together, providing an exceptional >9-year (111 months) median survival increase for non-IQSEC1-ARF5/6-amplified patients (across 9307 patients)." (PMID 33712589, 2021). "Arf6 can regulate tumor cell proliferation, migration and invasion via the ERK signaling pathway." (PMID 32822124, 2020). "ARF6 is also necessary for Human Growth Factor (HGF)-induced tumor angiogenesis and growth." (PMID 32426352, 2020). "Moreover, an ARF6-mediated site-directed targeting of matrix metalloprotease MT1-MMP also facilitates tumor cell invasion." (PMID 31792062, 2019). "Thus, AMAP1 appears to be crucial for invasiveness of PyMT-tumor cells, likely via upregulating plasma membrane dynamics to be consistent with a basic role of Arf6." (PMID 29329590, 2018). "Silencing of Arf6 also blocked the invasion of PyMT-tumor cells." (PMID 29329590, 2018). "We then analyzed an involvement of AMAP1, as well as Arf6, in invasion of these tumor cells." (PMID 29329590, 2018). "We sought to define the mechanism by which Arf6 drives the overgrowth of RasV12 tumours." (PMID 28281543, 2017). "Here, we show that Arf6 regulates developmental and tumor lymphangiogenesis in mice." (PMID 28900118, 2017).
tumor (continued). "We previously observed that Arf6 co-localizes with Hh in RasV12 cells and thus wondered whether Egfr modulates RasV12 tumour overgrowth by regulating an interaction between Arf6 and Hh." (PMID 28281543, 2017). "Thus, Arf6 in mLECs plays an important role in tumor lymphangiogenesis, thereby regulating cancer progression." (PMID 28900118, 2017). "Thus, Arf6 controls Hh trafficking in order to promote Hh signalling, which in turn cooperates with RasV12 to synergistically stimulate tumour overgrowth." (PMID 28281543, 2017). "Given our fly tumour data, we tested whether Arf6 serves as a molecular link in the cooperation between oncogenic Ras and Egfr in human cancer cells." (PMID 28281543, 2017). "Consistent with the possibility that Hh signalling could be involved in Egfr/Arf6-mediated Ras tumour overgrowth, we found that Hh was upregulated and co-localized with Arf6 in RasV12 clones." (PMID 28281543, 2017). "Finally, we demonstrated in this study that Arf6 in LECs is a key molecule for tumor lymphangiogenesis and cancer progression." (PMID 28900118, 2017). "Furthermore, we clarified that Arf6 in LECs plays pivotal roles in tumor lymphangiogenesis and cancer progression, giving a new cancer therapeutic opportunity." (PMID 28900118, 2017). "The tumor volume produced was significantly reduced by knockout of Arf6 in mLECs." (PMID 28900118, 2017). "Correlated to this result, tumor lymphangiogenesis was suppressed by Arf6 knockout." (PMID 28900118, 2017). "Finally, using immunofluorescence, we found that both spheres formed from primary S2B11 tumor cells and the tumor tissue itself expressed high levels of Ki-67, K14, ARF6 and RoR." (PMID 27374087, 2016). "We have found similar results for ARF6 when examining tumor grade." (PMID 26908458, 2016). "Thus, 77 and 73% of tumour and normal samples respectively showed ARF6 staining in >60% of the tissue sample." (PMID 26185744, 2015). "Therefore, presence of the Arf6 pathway would render tumor cells the potential to not only move-out from their original sites but also to be resistant to the ioninzing-radiation used in BCT." (PMID 24116160, 2013). "Thus, the effect of Arf6 inhibition in these tumor cell lines was highly reminiscent of that in human fibroblasts and MEFs." (PMID 23453597, 2013). "Such properties and regulation of AMAP1 and Arf6 mRNAs might have hindered these mRNAs from being identified previously to be correlated with tumor malignancy and recurrence." (PMID 24116160, 2013). "In addition to membrane trafficking, arf6 cellular functions include: actin remodeling, cell adhesion, redistribution of β1 integrins, phagocytosis, cell division, and tumor-cell invasion." (PMID 17397547, 2007). "Thus, our data suggest that ARF6 activation might promote tumor cell survival through ERK-mediated anti-apoptotic signaling." (PMID 40909781, 2025). "Inhibiting Arf6 activity could inhibit tumor invasion and metastasis." (PMID 38183097, 2024). "Furthermore, to investigate the potential application of targeting the ARF6 pathway in immunotherapy, we conducted experiments, in collaboration with Ono Pharmaceutical, using a tumor formation model with KPC cells transplanted into syngeneic mice so to evaluate the anticancer effect of ICIs." (PMID 39682280, 2024). "Interestingly, sites of active MV release serve as convergence points of multiple intracellular trafficking pathways, of which many components are subsequently loaded in tumor MVs, such as the Ras-related GTPases RhoA, Rab22a, and Rab35, and the ADP-ribosylation factor 6 (ARF6)." (PMID 37760395, 2023). "In addition, elucidation of the detailed molecular mechanisms of tumor malignancy involving ARF6 signaling may also provide clues to new therapeutic targets and strategies." (PMID 37834383, 2023). "Thus, inhibitors of the ARF6-dependent signaling pathway could be useful to control specifically tumor invasion and angiogenesis." (PMID 32426352, 2020).
tumor (continued). "Thus, MMTV-PyMT mice provide an animal model system to study Arf6-based tumor malignancy." (PMID 29329590, 2018). "In an effort to further elucidate how Egfr promotes oncogenic Ras-driven tumour overgrowth, we knocked down Egfr effectors (Drk and Arf6) by RNAi and asked whether this suppress oncogenic Ras-mediated tumour overgrowth, and identified Arf6 as a mediator of Ras tumour overgrowth." (PMID 28281543, 2017). "Thus, Arf6 plays critical roles in tumor lymphangiogenesis/angiogenesis and cancer metastasis." (PMID 28900118, 2017). "Thus, it awaits to be clarified as to whether circulating tumour cells, as well as tumours at metastatic sites in ccRCCs patients frequently express these proteins of the Arf6-based mesenchymal pathway at high levels." (PMID 26854204, 2016). "Finally, recent studies have established that cancer cells utilize Arf6-dependent mechanisms to generate and release plasma-membrane derived microvesicles containing proteases and other factors that can promote invasion and tumor progression." (PMID 25762935, 2015). "Therefore, cell populations that overexpress ARF6 near cell membranes in the tumor penumbra may have a powerful advantage with regard to invasiveness and metastasis." (PMID 25216519, 2014). "Indeed, genetic activation of ARF6 dramatically reduced apoptosis after 48 hours of vemurafenib, whereas silencing of Arf6 significantly increased apoptosis induced by vemurafenib, consistent with a role for ARF6 in early tumor cell survival during targeted therapy." (PMID 40909781, 2025). "Based on these traits, ARF6 migration to lamellipodia via SGs likely conveys an advantage in motility in peripheral PDAC cells, ultimately providing the tumor with enhanced invasive and metastatic capabilities." (PMID 38474168, 2024). "The ARF6 knockout or knockdown of its activator, the guanine exchange factor GRP1, significantly diminishes HGF-dependent angiogenesis and tumor growth in mice." (PMID 39769452, 2024). "For example, ARF6 (ADP-ribosylation factor 6), a small GTP binding protein present in tumor-derived microvesicles, is probably involved in the secretion of proteases of tumor cells." (PMID 39766306, 2024). "MVs also carry ADP-ribosylation factor 6 (ARF6) and ESCRT family that help facilitate cell-cell communication in tumor cells." (PMID 37025182, 2023). "It is worth mentioning that knocking down ARF6 also disrupted the PM localization of EGFR mutants and inhibited the growth of tumor cells." (PMID 36224181, 2022). "In this study, we also provided evidence that AR decoction inhibited tumor proliferation in CRC mice, and inhibited Wnt5/β-catenin signaling and the expression of ARF6 and N-Cadnerin in tumors of CRC mice." (PMID 34991661, 2022). "XIST knockdown inhibited ARF6, N-cad, GLUT1, and LDHA protein expression and increased E-cad protein expression in tumor tissues." (PMID 35899235, 2022). "To examine the clinical relevance of DDR1 and ARF6 in HCC, we evaluated the protein and phosphorylation levels of DDR1 and ARF6-GTP in a cohort of 50 paired HCC tissues and peripheral non-tumor tissue samples from Tongji hospital by western blot." (PMID 35140331, 2022). "The silencing of KCNQ1OT1 inhibited GC tumor growth, reduced cell proliferation, and induced GC cell apoptosis by binding to miR-145-5p, modulating the expression of ADP-Ribosylation Factor 6 (ARF6)." (PMID 34827600, 2021). "We evaluated the gene expression of miR-525-5p, ARF6, PCNA and CDK2 in the xenograft tumor tissues by RT-qPCR." (PMID 34621682, 2021). "ARF6 and AMAP1 are overexpressed in PC and ARF6 activation can down-regulate E-cadherin and upregulate focal adhesion turnover, thus promoting tumor invasion and metastasis." (PMID 32158356, 2020). "So far, work on mammalian PSDs has revealed functions for C-terminal domains in regulating ARF6, ARF1 or ARL14 during actin cytoskeletal reorganisation and membrane ruffling, tumour formation, axon regeneration and immune regulation." (PMID 31718774, 2019).
tumor (continued). "We first examined the protein expression of Arf6, AMAP1 and GEP100 by western blotting of whole tumor lysates, isolated from MMTV-PyMT mice and MMTV-Neu mice." (PMID 29329590, 2018). "By modulating the activity of ARF6 through knockdown of a nucleotide exchange factor, GEP100, tumor metastasis to the lung was impaired." (PMID 26908458, 2016). "Doxycycline-induced knockdown of ARF6 significantly reduced tumor growth in vivo, demonstrating that ARF6 has a role in tumor progression that is independent of the ARF6-mediated adaptive immune suppression we observed in immunocompetent mice." (PMID 40909781, 2025). "Highly expressed CD24 competitively binds to ADP-ribosylation factor 6(Arf6) with G protein-coupled receptor kinase-interactor 2(GIT2) and stabilizes Arf6-GTP to activate subsequent ERK pathways, thereby significantly promoting tumor metastasis and 5-FU chemoresistance." (PMID 40486886, 2025). "Furthermore, statins, which are MVP inhibitors, inhibited ARF6 activation and invasiveness in PDAC cells and decreased the resistance of tumor cells to chemotherapeutic drugs." (PMID 39682280, 2024). "Furthermore, although the mechanism of ARF6 packaging into exosomes is unknown, it stands that ARF6 was overexpressed in cells in protrusions in the cell membrane at the invasive fronts of PDACs—which are consequently more mobile—relative to the cells of the main tumor body." (PMID 38474168, 2024). "We found that phosphorylated STAT3 and ARF6 were significantly upregulated in tumor tissues compared with corresponding adjacent non-tumor tissues." (PMID 37716993, 2023). "Previous studies suggest that activated ARF6 plays important role in tumor progression, we wondered whether DDR1 could regulate ARF6 activation." (PMID 35140331, 2022). "The results indicated that DDR1, phosphorylated DDR1 and ARF6-GTP were significantly upregulated in tumor tissues compared with corresponding adjacent non-tumor tissues." (PMID 35140331, 2022). "Combining the previous observations with our results, we propose that ARF6 and EGFR might regulate the activity of each other to promote tumor progression by forming a positive feedback loop." (PMID 36224181, 2022). "Here the authors show that small GTPase ARF6 mediates the trafficking of palmitoylated EGFR from Golgi to plasma membrane and the blockade of this sorting system inhibits the growth of EGFR overexpression tumours." (PMID 36224181, 2022). "Compared with previous articles, the novelty of this study lies in the confirmation that XIST downregulation might inhibit tumor migration, invasion, and glycolysis, and the construction of a novel network mechanism of the XIST-miR-320d-ARF6 axis." (PMID 35899235, 2022). "Several mechanisms have been determined to influence cargo selection in EVs, notably the ADP-ribosylation factor 6 (ARF-6)-Exportin-5 axis, where ARF6-GTP interacts with Exportin-5 to deliver miRNA into tumor microvesicles (MVs) in an ARF6-GTP dependent manner." (PMID 36467419, 2022). "The small GTPase protein ARF6 has been proved to play a non-negligible role in promoting the proliferation, invasion and migration of a variety of tumor cells." (PMID 34991661, 2022). "Interestingly, Arf6 works with RhoA, the main activator of ROCK1, to generate tumor-derived microvesicles, suggesting a potential role for the R-Ras family in this process." (PMID 34530870, 2021). "Specifically, blocking the ARF6–PLD-1 pathway with NAV2729 inhibited baseline cytotoxicity of NK cells against tumor targets in the absence of antibody." (PMID 30647406, 2019). "Egfr promotes tumour overgrowth independent of the canonical the Sos/Ras signalling, instead it acts via the ADP-Ribosylation Factor 6 (Arf6)." (PMID 28281543, 2017). "Arf6 knockdown in otherwise wild-type clones showed no detectable growth defects but potently suppressed RasV12 tumour overgrowth (3a–c; quantified in 3e)." (PMID 28281543, 2017).